ENSG00000300293 (novel protein similar to claudin-7)
Gene: Protein-coding gene on chromosome X (40,834,445 to 40,934,085, forward strand). Ensembl gene ENSG00000300293.
Homologues: Orthologues: tropical clawed frog mkrn1 (55% identical), zebrafish mkrn1 (50% identical), Drosophila melanogaster Mkrn1 (27% identical), Caenorhabditis elegans lep-2 (27% identical), Drosophila melanogaster CG5347 (24% identical), Drosophila melanogaster CG5334 (18% identical), Drosophila melanogaster CG12477 (16% identical). Paralogues in human: MKRN1 (78% identical), MKRN3 (47% identical), MKRN2 (32% identical).